LUM (lumican)
Diseases named in the same sentence as LUM in open-access papers (continued):
Sharing a sentence is not in itself a finding about the gene and the disease.
gastric cancer (20 papers, 2008 to 2024). A primary or metastatic malignant neoplasm involving the stomach. "Exosomal LUM is also associated with diagnostic and prognostic value in different malignancies including neuroblastoma and gastric cancer." (PMID 39766023, 2024). "LUM encodes a member of a small leucine-rich proteoglycan family that regulates the collagen fibril organization and predicts poor overall survival in gastric cancer." (PMID 34566988, 2021). "In contrast, high lumican expression was associated with reduced survival and higher rates of metastasis in advanced colorectal cancer and gastric cancer." (PMID 34231169, 2021). "For example, LUM-associated CAFs may be involved in the proliferation and survival of tumor cells, whereas pericyte CAFs may be involved in neovascularization, thereby underscoring the functional heterogeneity of CAFs in gastric cancer." (PMID 34642171, 2022). "In gastric cancer, overexpressed LUM increases the risks of poor prognostic outcomes by activating 14 signaling pathways." (PMID 37692065, 2023). "First, although differential expression of LUM was detected between early gastric cancer, advanced gastric cancer and tumor-adjacent tissues, the prognostic implication of this finding has not been demonstrated." (PMID 38129820, 2023). "In a previous study, gastric cancer cells co-cultured with LUM knockout CAFs exhibited significantly reduced proliferation and metastasis in vivo." (PMID 37692065, 2023). "In gastric cancer, Lumican expression in tumor tissues is significantly higher than that in adjacent nontumor tissues." (PMID 36361971, 2022). "Two articles also showed that CAFs-derived FAP or lumican promoted gastric cancer progression, and their expression was related to poor clinical outcomes." (PMID 35864535, 2022). "LUM is highly expressed in fibroblasts in gastric cancer Cells (CAF) and regulates the FAK signaling pathway by activating integrin beta 1 to promote cancer cell dissemination." (PMID 34888227, 2021). "Functional enrichment analysis in gastric cancer genomic data showed an upregulation of lumican gene expression with relation to ECM interactions." (PMID 32500021, 2020). "Only one study reported that CAFs could activate FAK signaling in gastric cancer cells through the production of the extracellular protein lumican." (PMID 38355577, 2024). "This study is the first to identify LUM as a possible key oncogene in gastric cancer progression and the first to comprehensively analyze the relationship between LUM expression and tumor immune infiltration and ceRNA networks in gastric cancer." (PMID 38129820, 2023). "Our study indicates that the interplay of H. pylori, fibroblasts, and cancer cells induces inflammatory cytokine release to promote the transition of NFs to CAFs by showing an increased expression of FAP and Lumican in NFs co-culture with H. pylori and gastric cancer cells." (PMID 35864535, 2022). "A high lumican expression in gastric cancer tissues indicates a poor patient prognosis." (PMID 34572532, 2021). "Indeed, lumican promotes gastric cancer cell growth by activating the integrin β1/FAK signaling axis." (PMID 34572532, 2021). "I with a logFC >1, we generated a gene signature of iGC stage progression (intestinal-type gastric cancer progression signature - iGCPS), composed of APOD, COL1A2, GEM, FSTL1, LUM and SPARC." (PMID 39563861, 2024). "LUM contributes to the tumorigenesis and metastasis of gastric cancer by activating integrin β1-FAK signaling and its expression correlates with the invasive potential demonstrated in gastric cancer patient samples." (PMID 31861249, 2019). "As stated, this study identified several genes, such as LUM and NEK6, which were not previously associated with human gastric cancer." (PMID 18827816, 2008). "Furthermore, the TCGA database analysis showed a higher expression of lumican in the gastric cancer tissues than the neighboring non-tumor tissues." (PMID 34572532, 2021).
gastric cancer (continued). "Three of these are known to be involved in gastric cancer: MMP7, SPARC, and SOD2, and the other four have no such reported associations (INHBA, IGFBP7, NEK6, and LUM)." (PMID 18827816, 2008).
myopia (19 papers, 2008 to 2025). "Research suggests LUM variants and polymorphisms are potentially associated with human myopia, playing a role in binding collagen fibrils and constricting their diameter to regulate scleral size." (PMID 38821055, 2024). "Previously, the most well-known studies conducted among Taiwanese and Japanese populations have identified significant associations of high myopia with the lumican gene SNPs rs3759223 and rs3741834 and the SNP rs577948 on chromosome 11q24.1." (PMID 39062192, 2024). "A single nucleotide polymorphism in the 5′-regulatory region of the LUM gene (LUM) is associated with high myopia in some Asian populations but has a protective effect against myopia in a cohort of English patients." (PMID 38474072, 2024). "Genetic studies of gene polymorphisms in humans also support a role for lumican in scleral involvement of myopia which is closely associated with fibromodulin." (PMID 35571611, 2022). "In conclusion, this meta-analysis provides evidence that LUM polymorphism is associated with an increased risk of high myopia." (PMID 24956166, 2014). "To date, many case-control studies have been carried out to investigate the role of LUM gene polymorphism in the development of high myopia." (PMID 24956166, 2014). "This meta-analysis aims to comprehensively evaluate the relationship between two common LUM polymorphisms (rs3759223 and rs3759222) and the risk of high myopia." (PMID 24956166, 2014). "Animal studies have shown that Lum−/−Fmod−/− double-deficient mice demonstrate the physical signs of high myopia, including axial extension, scleral thinning, and retinal detachment, which suggest the LUM gene as a candidate gene for high myopia." (PMID 24956166, 2014). "Many studies have evaluated the association between lumican (LUM) gene polymorphisms and high myopia." (PMID 24956166, 2014). "Another mouse study also implicated the proteoglycans-lumican and fibromodulin as functional candidate genes for high myopia." (PMID 20339468, 2009). "Lumican (LUM) is one of the genes reported to be associated with myopia in many studies." (PMID 27711221, 2016). "There is evidence suggesting that this characteristic may be pertinent in humans and lumican gene polymorphisms could be related to high myopia." (PMID 24558602, 2013). "Genetic studies of gene polymorphisms in man also support a role for lumican in myopia." (PMID 24558602, 2013). "Research by analyzing DNA of patients' blood in Taiwan indicated that an SNP of the lumican gene might confer susceptibility to high myopia." (PMID 20339468, 2009). "This study suggests that LUM may be a key gene associated with myopia." (PMID 27711221, 2016). "The Lumican-Fibromodulin double knockout mice displayed features of pathological myopia, including scleral thinning and retinal detachment." (PMID 40909333, 2025). "In contrast, the lumican (LUM) gene has been studied by Chinese scholars in the field of high myopia or pathological myopia and is an important factor in maintaining the biomechanical properties of the sclera." (PMID 35186229, 2022). "In a Chinese cohort in Taiwan, an SNP in the lumican (LUM) protein on the 12q21.3-q22 gene was significantly higher presenting among myopia patients; it resulted in lower luciferase assay activity compared to the wild variety." (PMID 35327754, 2022). "These included FBN1, ADAMTS2 and TGFB2 which associate with connective tissue disorders (Marfan, Ehlers-Danlos and Loeys-Dietz syndromes), and the LUM-DCN-KERA gene complex involved in myopia, corneal dystrophies and cornea plana." (PMID 29760442, 2018). "Extracellular matrix components such as collagen type I alpha 1 (COL1A1), collagen type II alpha 1 (COL2A1), lumican (LUM), decorin (DCN) and epiphycan (EPYC or DSPG3) have been previously assessed for genetic associations with myopia." (PMID 23077567, 2012). "Lumican (LUM) is a candidate gene for myopia in the MYP3 locus." (PMID 27711221, 2016).
myopia (continued). "Given that increased axial length, retinal detachment and scleral thinning may be features of myopia, there is evidence that lumican may play a role in this disease." (PMID 24558602, 2013). "The potential role of lumican in myopia is also supported by animal studies." (PMID 24558602, 2013). "This may indicate a role for lumican, as well as aggrecan, in age-related extracellular matrix changes which may lead to myopia." (PMID 24558602, 2013). "Apart from EGR1, myopia-like changes has been observed in lumican-fibromodulin double null mice." (PMID 18636116, 2008). "Alterations in lumican may thus contribute to myopia and various retinal diseases." (PMID 35571611, 2022). "Therefore, hopefully, the mutant lumican transgenic mouse can play a role in the investigation of the pathogenesis of high myopia and may elucidate factors related to the scleral changes." (PMID 27711221, 2016). "Similarly, no mutation in the lumican and fibromodulin genes has been identified in families with high myopia, although a report claimed an association of myopia with SNPs of lumican." (PMID 18636116, 2008). "In ophthalmology, the absence of Lumican leads to conditions such as corneal opacification, glaucoma and myopia, highlighting its essential role in maintaining the normal structure of collagen fibres." (PMID 40537154, 2025). "Two genes, TGFB-induced factor homeobox 1 (TGIF) and lumican, have been excluded as candidate genes for high myopia, but they have still been treated as potential candidate genes in several subsequent studies." (PMID 18636116, 2008).
lung carcinoma (17 papers, 2015 to 2024). "Depletion of lumican associated with the downregulation of p120 catenin results in chromosome missegregation in lung cancer cell lines." (PMID 35660718, 2022). "Lumican is overexpressed in lung cancer cells and implicated in tumorigenesis and regulation of cancer cell invasion." (PMID 35660718, 2022). "Through that signaling, the mechanical effects of lumican were implicated in the modulation of microtubule dynamics and p120ctn signaling that governed the lung cancer cell invasion." (PMID 29549325, 2018). "Our data indicated that lumican is associated with microtubule-modulated p120ctn signaling, providing important insights into lung cancer progression." (PMID 29549325, 2018). "Furthermore, the loss-of-lumican decreased the subcellular distribution of p120ctn protein, a finding which indicates a possible mechanism for lumican in lung cancer cell invasion through p120ctn signaling." (PMID 29549325, 2018). "According to previous reports, the elevated expression of LUM in lung cancer cells promotes the metastatic potential of lung cancer cells via autocrine regulatory mechanism." (PMID 39766023, 2024). "Two genes, periostin (POSTN) and lumican (LUM) were upregulated in both severe asthmatics and lung cancer patients respectively." (PMID 35406434, 2022). "In lung cancer, Lumican is highly expressed in osteotropic lung cancer cells, with an enhanced capacity of bone metastasis." (PMID 36361971, 2022). "On the other hand, the introduction of exogenous lumican restored the motility of lumican knockdown cells and enhanced the invasion of lung cancer cells in the bone niche." (PMID 34572532, 2021). "In contrast, a separate study reported that the depletion of lumican increased lung cancer cell invasion." (PMID 34572532, 2021). "Exogenous lumican restored these reduced capacities of lumican knockdown cells and promoted the seeding of lung cancer cells in the bone microenvironment." (PMID 31963522, 2020). "Exogenous lumican was provided to study the autocrine regulation mechanism of lumican in the bone metastasis of lung cancer cells." (PMID 31963522, 2020). "Downregulation of lumican also decreased cell mobility and bone metastasis of the tumors in human A549 lung cancer cells." (PMID 31963522, 2020). "Taken together, these results indicated that lumican plays a specific role in bone metastasis in both mouse and human lung cancer cells." (PMID 31963522, 2020). "In the human lung cancer cell line, A549, lumican was found to promote cell proliferation by increasing the expression of Ras homolog gene family, member C (RhoC) and phosphorylated protein kinase B (p-Akt)." (PMID 31963522, 2020). "A decreased migration and invasion ability was observed in osteotropic lung cancer cell lines transfected with lumican-specific shRNAs." (PMID 31963522, 2020). "Our findings indicate that lumican modulates the interaction between lung cancer cells and bone microenvironment and promotes the settlement of cancer cells in the bone through an autocrine regulatory mechanism." (PMID 31963522, 2020). "The focus of this study was to evaluate the role of lumican in bone metastasis of lung cancer cells." (PMID 31963522, 2020). "Previous studies demonstrated that the molecular weight of lumican in lung cancer is about 37–100 kDa, indicating the presence of multiple forms of glycosylated lumican." (PMID 31963522, 2020). "In the current study, we demonstrated that lumican was overexpressed in lung cancer cells exhibiting a higher capacity for bone metastasis." (PMID 31963522, 2020). "Plasma proteomic analysis has demonstrated that lumican levels were significantly higher in patients with lung cancer in comparison with normal subjects." (PMID 31437251, 2019). "To achieve efficient and specific lumican gene inhibition in lung cancer cells, we used siRNAs and shRNA to approach." (PMID 29549325, 2018).
lung carcinoma (continued). "In this study, we found lumican functioned as a tubulin-binding protein and the depletion of lumican by transfection with its specific shRNA increased lung cancer cell invasion." (PMID 29549325, 2018). "In lung cancers, lumican expression occurs in both cancer cells and stromal cells in adenocarcinoma and squamous cell carcinoma, and the expression of lumican in these cells differentially correlates with the clinicopathological findings in such cases." (PMID 29549325, 2018). "The depletion of lumican-induced microtubule instability and resulted in lung cancer cell invasion via the downregulation of p120ctn." (PMID 29549325, 2018). "Functional implications including a role of lumican in p120cn-mediated lung cancer cell invasion are discussed." (PMID 29549325, 2018). "In this study, we used siRNAs, shRNA, and sgRNAs of lumican approach to analyze the effects of lumican in lung cancer cells." (PMID 29549325, 2018). "To assess the responses of Rho and Rac to lumican depletion in lung cancer cells, we performed pull-down assays using GST fusion proteins that bind activated Rac or Rho." (PMID 29549325, 2018). "Like in our study, the most abundant form of LUM in cell culture medium from the A549 lung cancer cell line had a molecular mass of 50 kDa." (PMID 29088800, 2017). "We further analyzed lumican, one of the overexpressed proteins, in 88 resected lung AdCs and in 23 malignant PE cell-blocks (13 lung AdCs and 10 non-lung cancers) using immunohistochemistry." (PMID 25961303, 2015). "However, future studies are required to investigate the therapeutic effect of targeting lumican for lung cancer treatment." (PMID 35660718, 2022). "LUM was upregulated in the lung cancer dataset alone, as seen in the case of microarray analysis." (PMID 35406434, 2022). "This study demonstrated the previously unknown roles of lumican and p120ctn in lung cancer cell metastasis." (PMID 29549325, 2018). "This study also revealed the role of lumican-mediated lung cancer cell invasion played via p120ctn." (PMID 29549325, 2018). "The overexpression of lumican has been found in lung cancer cells; however, the functional role of lumican in lung cancer cells remains unclear." (PMID 29549325, 2018). "Furthermore, some investigators suggest that decorin and lumican inhibit tumor growth, particularly in prostate and lung cancer." (PMID 28789706, 2017). "In contrast, for the genes LUM and FOSB, lower expression in lung cancer patients denote poor survival." (PMID 35406434, 2022). "Several previous studies reported SLRP proteins in breast, pancreatic, colorectal, uterine cervical, prostate, and lung cancers, among others, highlighting the controversial roles of DCN and LUM in cancer biology." (PMID 26230845, 2015). "The overexpression of lumican was found in lung cancer cell lines, but not in human endothelial cells (HUVECs) or transformed lung fibroblasts (Beas-2B)." (PMID 29549325, 2018). "None of the lung cancer cell-blocks showed lumican immunoreaction, whereas those of all the other tumors were strongly positive." (PMID 25961303, 2015). "Finally, immunoblotting analysis showed lumican expression in both cell lysate and conditioned medium of a fibroblast culture but not in those of A549 lung cancer cell line." (PMID 25961303, 2015).